SNHG5 (small nucleolar RNA host gene 5)
Synonyms: MGC16362; bA33E24.2; U50HG; NCRNA00044; LINC00044; C6orf160
Gene: Long non-coding RNA gene on chromosome 6 (85,644,369 to 85,678,943, reverse strand). Ensembl gene ENSG00000203875.
Gene Ontology:
Biological process: RNA processing
Cellular component: nucleolus
Diseases named in the same sentence as SNHG5 in open-access papers:
SNHG5 is named in the same sentence as 77 diseases in open-access papers, as found by Europe PMC text mining. Sharing a sentence is not in itself a finding about the gene and the disease. The quoted sentences say what the papers report.
gastric cancer (21 papers, 2016 to 2026). A primary or metastatic malignant neoplasm involving the stomach. "SNHG5, the host gene of snoRNA U50, inhibits gastric cancer progression by sequestering metastasis-associated protein 2 (MTA2) in the cytoplasm, indicating its therapeutic value in gastric cancer." (PMID 41019058, 2025). "SNHG5 was also studied in gastric cancer, where SNHG5 was downregulated and associated with tumor, node and metastasis stage." (PMID 28415644, 2017). "In patients with gastric cancer, SNHG5 was significantly downregulated and associated with TNM stage." (PMID 27835598, 2016). "In contrast to its EMT-promoting role in CRC and HCC, SNHG5 has been reported to suppress EMT in gastric cancer by binding and retaining MTA2 in the cytoplasm, thereby inhibiting NuRD complex–mediated chromatin remodeling." (PMID 41550840, 2026). "Current study shows that E2F1 interacts with ARRDC1-AS1, so we infer that ARRDC1-AS1 has a similar function to SNHG5, and promotes the growth of gastric cancer cells by targeting E2F1." (PMID 37258567, 2023). "SNHG5 has been widely proven to play an important role in a variety of tumors, such as colorectal cancer, gastric cancer and osteosarcoma, and even myeloid leukemia." (PMID 35338348, 2022). "For example, the lncRNA PVT1 regulates malignant behavior in xenograft models of breast cancer cells, whereas small nucleolar RNA host gene 5 knockdown restrains the malignant phenotype of gastric cancer cells by targeting the miR-32/KLF4 axis." (PMID 31789416, 2020). "SNHG5 and JPX ranked 6th and 7th by CLING, are implicated in gastric cancer and breast cancer, respectively." (PMID 32211391, 2020). "But SNHG5 was found to be downregulated in gastric cancer and blocked gastric cancer progression by trapping MTA2." (PMID 32131767, 2020). "Another study reports that SNHG5 binds to miR‐32 in gastric cancer and inhibits the expression of miR‐32 in a RISC‐dependent manner, enhancing the ability of cell proliferation and migration." (PMID 32368853, 2020). "In contrast, other studies have indicated that SNHG5 functions as an oncogene in colorectal cancer, osteosarcoma, hepatocellular cancer, bladder cancer and gastric cancer." (PMID 30764831, 2019). "A study also revealed that SNHG5 suppresses gastric cancer progression by trapping MTA2 in the cytosol." (PMID 30764831, 2019). "In our previously study, we reported that, in gastric cancer, SNHG5 is downregulated and functions in a dual manner." (PMID 31885582, 2019). "The lncRNA SNHG5/miR-32 axis regulates gastric cancer cell proliferation and migration by targeting KLF4, in addition to regulating imatinib resistance in chronic myeloid leukemia via MiR-205-5p." (PMID 30250399, 2018). "The significantly downregulated SNHG5 in gastric cancer, thereby promoting gastric cancer progression." (PMID 29458374, 2018). "In gastric cancer, SNHG5 has been reported to function as a tumor suppressor." (PMID 41550840, 2026). "For example, Researchers have conducted in vivo and in vitro experiments to demonstrate that small nuclear RNA host gene (SNHG5) may be a new target for treating gastric cancer." (PMID 41019058, 2025). "SNHG5 was first revealed to be highly expressed as an oncogene in gastric cancer, and successive researchers subsequently reported that SNHG5 was differentially expressed in bladder cancer, lung cancer, liver cancer, cervical cancer, osteosarcoma, laryngeal cancer, oral cancer, and lymphoma." (PMID 38475928, 2024). "Notably, the silencing of SNHG5 using si-SNHG5 resulted in a decrease in miR-20a expression, thereby promoting the proliferation of gastric cancer cells." (PMID 38397398, 2024). "In the study of glioma, SNHG5 promotes tumor growth by targeting E2F3, and E2F3 and E2F1 are both transcription factors of the E2Fs encoding gene family and are associated with poor prognosis of gastric cancer." (PMID 37258567, 2023).
gastric cancer (continued). "Currently, lncRNA small nucleolar RNA host gene 5 (SNHG5) has been found to act as a tumor-promoting gene in bladder cancer and colorectal cancer and a suppressor gene in gastric cancer." (PMID 30250399, 2018). "For example, a lower expression of genes that may play an important role in suppressing gastric cancer (GKN1, LIPF, ANXA10, MUC6, PSCA, and SNHG5) was found." (PMID 35625760, 2022).
colorectal cancer (14 papers, 2016 to 2026). A primary or metastatic malignant neoplasm that affects the colon or rectum. "To assess the functional impact of Snhg5 on colorectal cancer cell behavior, we performed gain- and loss-of-function assays in both F0 and F3 MC38 sublines." (PMID 41550840, 2026). "Together, these results indicate that Snhg5 facilitates colorectal cancer cell proliferation, cell cycle progression, and motility while concurrently suppressing apoptosis, supporting its functional role in driving aggressive tumor phenotypes." (PMID 41550840, 2026). "On the other hand, SNHG5 was shown to have a cancer-promoting effect, as knockdown of SNHG5 inhibited the proliferation and apoptosis of breast cancer or colorectal cancer cell lines." (PMID 33176855, 2020). "For example, SNHG5 affects cell proliferation, metastasis and migration of colorectal cancer through regulating miR-132-3p/CREB5 and SNHG20 promotes the tumorigenesis of oral squamous cell carcinoma via targeting miR-197/LIN28 axis." (PMID 30858762, 2019). "For example, SNHG5 promotes colorectal cancer cell survival by counteracting STAU1-mediated mRNA destabilization." (PMID 30250399, 2018). "Here, the authors identify SNHG5 as a long non-coding RNA promoting proliferation and survival of colorectal cancer cells by protecting specific mRNAs from STAU1-mediated degradation." (PMID 28004750, 2016). "Here, we identify and characterize SNHG5 as a stable cytoplasmic lncRNA with up-regulated expression in colorectal cancer." (PMID 28004750, 2016). "Specifically, CREB5 has been shown to promote cell proliferation and correlate with a poor prognosis in hepatocellular carcinoma, while the lncRNA SNHG5 affects the cell proliferation, metastasis, and migration of colorectal cancer through regulating miR-132–3p/CREB5." (PMID 35754483, 2022). "SNHG5 promotes colorectal cancer by stabilizing its target SPATS2 via inhibiting SMD39." (PMID 32527996, 2020). "Hence, we characterize SNHG5 as a lncRNA promoting tumour cell survival in colorectal cancer and delineate a novel mechanism in which a cytoplasmic lncRNA functions through blocking the action of STAU1." (PMID 28004750, 2016). "Together, these findings indicate that the Snhg5/GNB2 axis promotes EMT and activates the Wnt/β-catenin pathway, thereby contributing to the metastatic phenotype of colorectal cancer cells." (PMID 41550840, 2026).
melanoma (13 papers, 2016 to 2026). A malignant, usually aggressive tumor composed of atypical, neoplastic melanocytes. "Higher SNHG5 expression has also been shown to be associated with higher melanoma stage." (PMID 38601651, 2024). "The study also found significantly higher serum SNHG5 expression in melanoma patients compared to healthy volunteers." (PMID 38601651, 2024). "Further analysis also revealed significantly greater SNHG5 levels in melanoma patients compared to patients with squamous cell carcinoma (p < 0.05)." (PMID 37629553, 2023). "In melanoma, the lncRNA SNHG5 was found to affect tumor development by regulating the miR-26a-5p/TRPC3 pathway." (PMID 35870973, 2022). "For instance, SNHG5 facilitates the growth and invasion of melanoma cells by targeting miR-26a-5p and elevating TRPC3 expression." (PMID 35166647, 2022). "The exogenous knockdown of SNHG5 in melanoma cells in vitro decreases their proliferation rate and invasive capacity, while it stimulated apoptosis." (PMID 32318335, 2020). "Through miR-26 sponging and up-regulation of TRPC3 (transient receptor potential channel 3), SNHG5 stimulates melanoma cell growth." (PMID 32318335, 2020). "The expression of SNHG5 was also assessed in tissue samples of 36 primary melanoma and in four nevi." (PMID 28415644, 2017). "The serum SNHG5 levels were significantly higher in 24 patients with melanoma compared to 15 healthy subjects and 5 patients with squamous cell carcinoma (SCC)." (PMID 28415644, 2017). "Furthermore, pro-metastatic phenotypes driven by SNHG5–miRNA interactions have been observed in melanoma and osteosarcoma, where SNHG5 promotes invasion via the miR-26a-5p/TRPC3 axis." (PMID 41550840, 2026). "Conversely, SNHG5 (Small Nucleolar RNA Host Gene 5) is upregulated in melanoma cells." (PMID 40076754, 2025). "Previously, higher SNHG5 lncRNA expression has been described in melanoma cell lines and tissues." (PMID 38601651, 2024). "In addition to PVT1, lncRNA small nucleolar RNA host gene 5 (SNHG5) has emerged as a potential melanoma marker." (PMID 37629553, 2023). "SNHG5 plays an analogous role in melanoma by regulating the miR-26a-5p/TRPC3 pathway." (PMID 33392203, 2020). "In five patients with melanoma, the serum levels of SNHG5 were assessed before and after surgery." (PMID 28415644, 2017). "As such, the researchers concluded that the serum SNHG5 level acts as a biomarker for melanoma-bearing status, rather than a marker of cancer progression." (PMID 37629553, 2023). "The expression levels of ANRIL and SNHG5 in primary melanoma samples have so far been compared with normal tissue only and have not yet been studied in relation to melanoma stage." (PMID 28415644, 2017). "The mechanism by which SNHG5 might interfere with the pathogenesis of malignant melanoma is not known yet." (PMID 28415644, 2017).
glioma (12 papers, 2019 to 2026). A benign or malignant brain and spinal cord tumor that arises from glial cells (astrocytes, oligodendrocytes, ependymal cells). "In glioma, SNHG5 sponges miR-205 to upregulate E2F3, thereby increasing glucose uptake and lactate production." (PMID 41550840, 2026). "Previous studies have reported that SNHG5 is highly expressed in gliomas, where it promotes glucose uptake and enhances cell migration and invasion capabilities." (PMID 41234719, 2025). "In glioma, SNHG5 is highly expressed, and its knockdown blocks the viability and invasion of glioma cells through regulating Wnt/β-catenin signal pathway." (PMID 35166647, 2022). "By acting as a sponge for miR-205, which targets E2F transcription factor 3 (E2F3), SNHG5 enhances glioma growth." (PMID 33652661, 2021). "The results indicated that compared with normal tissues, the expression level of SNHG5 is significantly increased in gliomas." (PMID 31292168, 2019). "SNHG5 promotes the glucose uptake, migration and invasion of glioma cells by sponging miR-205 and up-regulating E2F3 expression." (PMID 31292168, 2019). "Next, through a series of assays, we concluded that SNHG5 functions as a sponge for miR-205, which inhibits tumour growth in glioma by targeting E2F transcription factor 3 (E2F3)." (PMID 31292168, 2019). "First, we found that SNHG5 expression was higher in glioma and was related to glioma glucose uptake, migration and invasion." (PMID 31292168, 2019). "Second, through a series of assays, we concluded that SNHG5 acts as a sponge for miR-205, which inhibits tumour growth in glioma by targeting E2F transcription factor 3 (E2F3)." (PMID 31292168, 2019). "In the present study, we aimed to explore the molecular mechanism of small nucleolar RNA host gene 5 (SNHG5) in glioma progression." (PMID 31292168, 2019). "Taken together, we found that SNHG5 modulates glioma progression by sponging miR-205 to up-regulate E2F3 expression." (PMID 31292168, 2019). "In our study, we reported that SNHG5 was overexpressed in glioma and found that SNHG5 promotes the glucose uptake, migration and invasion of glioma cells." (PMID 31292168, 2019). "Our study found an increase in the expression of SNHG5 in glioma and that SNHG5 was closely related to glioma glucose uptake, migration and invasion." (PMID 31292168, 2019). "Snhg5 has also been reported to participate in the occurrence and development of glioma." (PMID 38110334, 2023). "Our study not only furthers the understanding of the regulatory mechanism of the SNHG5/miR-205/E2F3 axis in glioma but also may lead to a new potential strategy for glioma therapy." (PMID 31292168, 2019). "To determine whether SNHG5 can interact with miR-205 in glioma, we performed the following experiments." (PMID 31292168, 2019). "Taken together, our results show that the SNHG5/miR-205/E2F3 axis is involved in glioma progression and may provide a new therapeutic target for the diagnosis and therapy of glioma." (PMID 31292168, 2019). "In the present study, we hypothesized that SNHG5 might target miRNAs in glioma, and we identified the binding sites between miR-205 and SNHG5 through bioinformatics analysis." (PMID 31292168, 2019). "Second, through qRT-PCR, we determined that miR-205 expression levels were up-regulated after down-regulating SNHG5 in glioma cells and that miR-205 mimics could also down-regulate SNHG5 expression levels in glioma cells." (PMID 31292168, 2019). "We constructed a glioma xenograft model to measure the role of SNHG5 in vivo." (PMID 31292168, 2019). "We intensively investigated whether SNHG5 drives the glucose uptake, migration and invasion of glioma cell lines via E2F3 in a miR-205-dependent manner." (PMID 31292168, 2019). "Our present study showed that SNHG5 promotes the expression of E2F3 in glioma." (PMID 31292168, 2019). "In summary, we revealed that SNHG5 is a novel oncogene in glioma." (PMID 31292168, 2019).
glioma (continued). "Next, we detected the expression of SNHG5 in glioma tissues (n=20) and normal brain tissues (n=20)." (PMID 31292168, 2019). "Additionally, we detected a significant increase in SNHG5 expression in glioma cell lines (U87 and U251) compared with that in NHAs." (PMID 31292168, 2019). "Taken together, these results suggest that SNHG5 may be a potential prognostic factor and therapeutic target for glioma." (PMID 31292168, 2019). "Interestingly, SNHG5 promoted the development of glioma by targeting E2F3." (PMID 33381564, 2020). "Additionally, we verified that SNHG5 enhances the expression of E2F3 by competitively binding to miR-205 and that the effect of si-SNHG5 on glioma cells could be impaired by the miR-205 inhibitor." (PMID 31292168, 2019). "We wondered whether SNHG5 could affect glucose metabolism in glioma." (PMID 31292168, 2019). "Finally, we demonstrated that SNHG5 enhanced the progression of glioma in vivo." (PMID 31292168, 2019). "Although multiple studies have shown that SNHG5 plays an oncogenic role in some human cancers, including gastric adenocarcinoma, liver cancer and osteosarcoma, the mechanism of SNHG5 in glioma has not been thoroughly expounded." (PMID 31292168, 2019). "First, we analysed the expression profiles of SNHG5 in the TCGA database and found that the expression level of SNHG5 in glioma tissues was significantly higher than that in non-malignant tissues." (PMID 31292168, 2019). "Unlike its pro-tumorigenic function in gliomas and other tumors, SNHG5 may act as a tumor suppressor in thyroid cancer." (PMID 41234719, 2025). "However, there are no reports on the molecular mechanism of SNHG5 in glioma." (PMID 31292168, 2019).
breast carcinoma (11 papers, 2020 to 2026). "Furthermore, in breast cancer–associated fibroblasts (CAFs), SNHG5 stabilizes ZNF281 mRNA through an m6A-dependent mechanism, upregulating CCL2/CCL5 expression and activating p38 MAPK signaling, which enhances vascular permeability and neovascularization to facilitate PMN formation." (PMID 41550840, 2026). "In breast cancer, SNHG5 activates a metabolic reprogramming program by regulating BACH1 through miR-299, thereby upregulating glycolytic enzymes such as HK2 and PFK1, and promoting proliferation via enhanced aerobic glycolysis." (PMID 41550840, 2026). "For instance, in breast cancer, SNHG5 regulates proliferation through the SNHG5–miR-154-5p–PCNA axis; in HCC, it sponges miR-26a-5p to relieve repression of GSK3β, leading to Wnt/β-catenin pathway activation and EMT induction." (PMID 41550840, 2026). "Similar ceRNA networks involving SNHG5 have been reported in other malignancies, including the SNHG5–miR-154-5p–PCNA axis in breast cancer and the SNHG5–miR-26a-5p–GSK3β axis in HCC." (PMID 41550840, 2026). "SNHG5 has also been shown to enhance glycolytic flux in breast cancer through the miR-299/BACH1 axis, promoting the expression of glycolytic enzymes such as HK2, PFK1, and GAPDH." (PMID 41550840, 2026). "For example, SNHG5 can promote the proliferation and cell cycle progression of breast cancer cells by stimulating the overexpression of proliferating cell nuclear antigen (PCNA)." (PMID 35855425, 2022).
osteosarcoma (10 papers, 2018 to 2026). A usually aggressive malignant bone-forming mesenchymal neoplasm, predominantly affecting adolescents and young adults. "The expression of SNHG5 is elevated in patients with osteosarcoma, which correlates with poor clinical outcomes and prognosis." (PMID 37278038, 2023). "The results of transwell assays showed that overexpression of SNHG5 and inhibition of miR-212-3p could extenuate the reduction of invasion, and migration of si-SGK3, which showed LncRNA SNHG5/miR-212-3p/SGK3 axis regulate the progression of osteosarcoma." (PMID 30250399, 2018). "However, the function of SNHG5 in osteosarcoma remains unclear, thus driving us to explore the role of SNHG5 in OS." (PMID 30250399, 2018). "Consequently, these conclusions showed that lncRNA SNHG5 plays as a critical role in OS tumorigenesis—indicating that SNHG5 may be a potential therapeutic target for osteosarcoma." (PMID 30250399, 2018). "Recent studies have shown SNHG1, SNHG5, SNHG16, and SNHG20 to be overexpressed in osteosarcoma tissues and play vital roles in promoting tumour progression." (PMID 37278038, 2023). "lncRNA SNHG5 acts as a sponge of miR-26a and competitively binds ROCK with miR-26a to promote the proliferation, invasion, and migration of osteosarcoma cells." (PMID 35246511, 2022). "High levels of SNHG5 function as a sponge for miR-26a and competitively bind miR-26a with ROCK, promoting osteosarcoma cell proliferation, invasion, and migration in osteosarcoma." (PMID 31248165, 2019).